CRP (C-reactive protein)
Diseases named in the same sentence as CRP in open-access papers (continued):
Sharing a sentence is not in itself a finding about the gene and the disease.
gallstones (32 papers, 2013 to 2026). Solid crystalline precipitates in the biliary tract, usually formed in the gallbladder, resulting in the condition of cholelithiasis. "CRP is associated with gallstone-related inflammation and disease severity, serving as a useful biomarker in gallbladder disorders." (PMID 40942916, 2025). "Another medical research on 4484 participants has found that CRP levels are associated with a greater prevalence of gallstones." (PMID 40942916, 2025). "In a study of the Kailuan cohort, high-sensitivity C-reactive protein (hs-CRP) was identified as an independent causal indicator of first-onset gallstones." (PMID 40247188, 2025). "Higher DII scores are also associated with the production of higher concentrations of TNF-α, IL-6, CRP, and a range of other factors that contribute to greater gallstone risk." (PMID 38779446, 2024). "The results of our subgroup analysis revealed that the odds of gallstones prevalence associated with Log (hs-CRP) level were particularly elevated in the 20–40-year age group compared to other age groups." (PMID 39600934, 2024). "The Western diet has been reported to significantly increase systemic inflammatory biomarkers such as CRP, IL-6, and IL-10, associated with an increased risk of gallstones." (PMID 38765815, 2024). "A prospective cohort analysis further demonstrated that CRP levels are independently associated with gallstone risk." (PMID 38779446, 2024). "It has been demonstrated that higher Log (hs-CRP) levels are associated with greater odds of gallstone prevalence, particularly in younger adults." (PMID 39600934, 2024). "Studies have revealed that inflammatory biomarkers such as IL-6, IL-8, TNF-α and CRP are associated with an increased risk of gallstones." (PMID 38765815, 2024). "High-sensitivity C-reactive protein (hs-CRP) concentrations were found to be strongly related to an increased risk of gallstones in a study by Tong Liu." (PMID 38283040, 2023). "Given the positive association of NSAIDs with sVEGFR3 and GRO in gallstones controls and with CRP in dysplasia cases, we added these three markers to the logistic regression model adjusted for age, sex and biliary colic for the subset of people with immune‐related marker data." (PMID 39482824, 2025). "In addition, a cohort study of 2,650 participants found significant associations between gallstones and both CRP levels and white blood cell count." (PMID 39867880, 2024). "Higher Log (hs-CRP) levels are linked to a greater prevalence of gallstones." (PMID 39600934, 2024). "For example, researchers found a link between the severity of acute cholecystitis and CRP levels in a US population, while another cross-sectional study of a US population found that a 1-unit increase in the TyG index was associated with a 25% higher risk of gallstones." (PMID 40988273, 2025). "The mechanisms underlying gallstone formation and CRP level remain unclear." (PMID 38394521, 2024). "Earlier research has looked at the connection between one measure (CRP or TyG index) and gallstones." (PMID 40988273, 2025). "So, previous studies have proven the association of CRP, Vitamin D, and AAST with gallstone classification." (PMID 40942916, 2025). "To date, this is the inaugural cross-sectional study to look at the relationship between hs-CRP and gallstones in a US adult population." (PMID 39600934, 2024). "A linear positive relationship was observed between Log (hs-CRP) and gallstone prevalence, which remained stable even in the fully adjusted model." (PMID 39600934, 2024). "In a study comparing patients with gallstones and healthy controls, high-sensitivity CRP levels were higher in patients with gallstones." (PMID 38394521, 2024). "A study detected a noteworthy correlation between gallstones and systemic markers of inflammation, notably white blood cell counts and CRP." (PMID 38903577, 2024).
gallstones (continued). "The prevalence of gallstones was 11.15%, increasing with higher Log (hs-CRP) levels (quartile 1: 8.31%; quartile 2: 8.76%; quartile 3: 11.98%; quartile 4: 16.36%; p < 0.0001)." (PMID 39600934, 2024). "CRP and total body water also had notable scores of 15.0 and 12.96, respectively, and these factors provided significant information for gallstone prediction." (PMID 38394521, 2024). "The smoothed fitting curve results demonstrated a linear and positive relationship between Log (hs-CRP) and the prevalence of gallstones." (PMID 39600934, 2024). "Some studies have focused on specific parameters, either ultrasound findings (gallbladder wall thickness, contracted gallbladder, impaction of gallstones at the neck of the gallbladder, and common bile duct stones) or laboratory markers (C-reactive protein)." (PMID 38618440, 2024). "The smoothed fitted curve showed a positive linear relationship between Log (hs-CRP) and gallstones prevalence." (PMID 39600934, 2024). "Compared to the lowest quartile of Log (hs-CRP), the odds of gallstones prevalence in the highest quartile increased by 66% [1.66 (1.26, 2.20)]." (PMID 39600934, 2024). "To further validate the stability of the correlation between Log (hs-CRP) and gallstones, we performed sensitivity analyses of Log (hs-CRP) from by interquartile level." (PMID 39600934, 2024). "Logistic regression analysis, subgroup analysis, and smoothed fitted curves were applied to determine the relationship between Log (hs-CRP) and the presence of gallstones." (PMID 39600934, 2024). "The results of the present study, a cross-sectional investigation involving 4,484 American adults, demonstrate a correlation between elevated Log (hs-CRP) values and an increased prevalence of gallstones." (PMID 39600934, 2024). "Subgroup analyses were performed to explore the relationship between gallstone prevalence and the stability of Log (hs-CRP) across different population groups." (PMID 39600934, 2024). "Other significant predictors of critical care admission on the univariate analysis were presence of gallstones (OR 0.43, 95% CI 0.20 to 0.90, p = 0.026) and CRP concentrations of ≥120 mg/L (OR 1.01, 95% CI 1.00 to 1.02, p = 0.0001)." (PMID 32859322, 2020). "This population-based study aims to investigate the association of the novel inflammation-lipid composite biomarker high-sensitivity C-reactive protein-to-HDL cholesterol ratio (CHR) with gallstones and evaluate whether MAFLD mediates this relationship." (PMID 40247188, 2025). "There were also significant differences in metabolic markers, with those with gallstones presenting higher fasting glucose levels (121.1 ± 42.0 vs 112.9 ± 37.3 mg/dL), a higher tyG index (8.7 ± 0.7 vs 8.5 ± 0.7), and higher CRP levels (2.8 vs 1.9 mg/dL) (all P < .001)." (PMID 40988273, 2025). "The experimental results showed that vitamin D, C-reactive protein (CRP) level, total body water, and lean mass are crucial features, and the gradient boosting technique achieved the highest accuracy (85.42%) in predicting gallstones." (PMID 38394521, 2024). "Subgroup analysis of the relationship between Log (hs-CRP) and gallstones." (PMID 39600934, 2024). "Our bioimpedance analysis and laboratory data showed that vitamin D level, CRP level, total body water, and fat-free mass are important features, and the gradient boosting technique achieved the highest accuracy of 85.42% in predicting gallstones." (PMID 38394521, 2024). "No significant intergroup differences were observed in age, sex, gallstone presence, CCI score, perforation status, CBD stone presence, need for endoscopic retrograde cholangiopancreatography (ERCP), PTGBD catheter indwelling time, WBC count, serum CRP, and gallstone size, and number." (PMID 35119038, 2022). "This suggests the superiority of NLR and PLR to CRP in predicting the course of gallstone AP." (PMID 29370777, 2018).
gallstones (continued). "So this research has shown that the individuals who have lower CRP, higher Vitamin D, and AAST, have a higher chance of gallstones." (PMID 40942916, 2025). "For example, gallstone patients had higher levels of IL‐6, IL‐10 and IL‐12p70 than population‐based controls, and GBC patients had increased levels of C‐reactive protein (CRP), CCL20, IL‐16, sTNFRI and sTNFRII compared to gallstones controls." (PMID 39482824, 2025). "In conclusion, both NLR and PLR were significant independent predictive factors of POF in gallstone AP, and they were better predictors of POF than was CRP, a traditionally used inflammatory marker and independent prognostic factor." (PMID 29370777, 2018). "Moreover, this research has identified CRP, Vitamin D, and AAST as the most influential features for gallstone prediction." (PMID 40942916, 2025). "Specifically, lowering the CRP value from 13.9 to values between 0.1 and 0.5 has been sufficient to change the prediction from gallstone-positive to gallstone-negative, while keeping Vitamin D and AAST largely unchanged." (PMID 40942916, 2025). "For index 76, an Fn prediction is incorrect, in which Vitamin D (10.9), AAST, and CRP (0.63) have pushed the prediction to be class 1 (gallstone negative)." (PMID 40942916, 2025). "In the dataset, the gallstone-positive individuals have a mean CRP of 0.46, which is lower than the negative individuals." (PMID 40942916, 2025). "In the study, compared with patients with gallstones, GBC patients showed higher levels of inflammation-related indicators, such as leukocytes, CRP, neutrophils, and lymphocytes, as well as multiple indicators related to liver injury and function, such as ALT, AST, and γ-GT." (PMID 36923422, 2023). "Notably, lower CRP levels have been associated with negative SHAP values, indicating a link with Class 0 (gallstone positive)." (PMID 40942916, 2025). "We found that patients with dysplasia had lower levels of IL‐33, BCA‐1, GRO, CCL19 (MIP‐3B), sTNFRII, CXCL6 (GCP2), CRP and MIP‐1B compared to gallstones patients without dysplasia." (PMID 39482824, 2025). "For the gallstone AP group, NLR and PLR demonstrated a predictive value significantly superior to C-reactive protein (CRP), whereas NLR, PLR, and CRP were not significant predictors for alcoholic AP." (PMID 29370777, 2018). "Additionally, BMI, SIRI, SII, NLR, CRP, and PIV levels were significantly higher in participants with gallstones than in those without." (PMID 39867880, 2024).
hematoma (32 papers, 2017 to 2026). A hematoma is a collection of blood from a vascular structure into an extravascular space. "Higher hematoma IL-1β was associated with higher plasma CRP (β-coefficient: 21.0; 95% CI: 4.4-37.5; n = 117 paired samples)." (PMID 42071280, 2026). "Other studies have shown that a higher CRP level on hospital admission was consistently associated with hematoma growth." (PMID 37464311, 2023). "In a cohort of 399 patients presenting with primary or vitamin K antagonist (VKA)-associated ICH plasma CRP levels, measured within 6 h from onset were significantly associated with the occurrence of hematoma growth and neurological worsening." (PMID 30254628, 2018). "Among Inflammation markers, plasma CRP has been reported particularly associated with early hematoma growth and early neurological worsening, as well as poor outcomes after ICH." (PMID 29930507, 2018). "Control of bleeding from the back muscles during PPS placement is often difficult and can cause a postoperative hematoma, which might cause elevation of the CRP level in the early postoperative period." (PMID 35207292, 2022). "This aligns with previous findings that plasma CRP levels rise markedly within 48 to 72 h after intracerebral hemorrhage, correlating with hematoma volume and indicating its prognostic relevance." (PMID 40672462, 2025). "A nomogram model for predicting poor prognosis in HICH patients was constructed using the NIHSS score, GCS score, creatinine level, hs-CRP level, hemorrhage location, hematoma volume, and HMOX1 mRNA level as predictive factors." (PMID 41404462, 2025). "Compared with the good prognosis group, the poor prognosis group had significantly greater NIHSS scores, hs-CRP levels, proportions of hemorrhages in the cerebral lobe and thalamus, hematoma volumes, and proportions of irregular hematoma shapes." (PMID 41404462, 2025). "The final model included 4 independent predictors (Glasgow Coma Scale, hematoma volume, rate-pressure product, c-reactive protein) and was developed as a simple-to-use nomogram." (PMID 38911585, 2024). "Levels of serum IL-12 was positively correlated with the admission of NIHSS scores (r = 0.535, P < 0.001), hematoma volume (r = 0.608, P < 0.001), serum CRP levels (r = 0.561, P < 0.001), and serum TNF-α levels (r = 0.533, P < 0.001) in 209 cases ICH patients." (PMID 36303589, 2022). "Clinical studies have reported associations between serum inflammatory markers in the acute phase of ICH, mainly CCL2, CXCL10, IL-6, IL-11, CRP, fibrinogen, and CSF cytokines with hematoma expansion and early neurological decline." (PMID 34439789, 2021). "The best models included an hs-CRP level ≥3 mg/L, age, baseline hematoma volume, NIHSS score, and HE." (PMID 33123072, 2020). "Plasma CRP increased markedly from 48 to 72 h from admission, and the magnitude of the response was related to hematoma volume at later time points." (PMID 30254628, 2018). "CRP levels >10 mg/L are predictive factors for early hematoma growth and worsening neurologic function in patients with acute spontaneous ICH36." (PMID 28361971, 2017). "This reduction in perfusion may inhibit the release of inflammatory mediators such as CRP, thereby alleviating tissue hematoma and pain signal transmission." (PMID 40868853, 2025). "Ascending tertiles of RDW reported lower BI scores (p = 0.001), higher RDW (p < 0.001), higher NIHSS1 scores (p < 0.001), higher NIHISS2 scores (p < 0.001), higher HAMD scores (p = 0.024), higher CRP (p < 0.001), higher hematoma volume (p < 0.001), and higher WBC (p = 0.007)." (PMID 37090985, 2023). "We also found that the baseline hematoma volume in patients with an hs-CRP level ≥3 mg/L (median: 37.3 ml) was over 2-fold higher than those in patients with an hs-CRP level <3 mg/L (median: 14.5 ml); the same trend was also evident for hematoma volume at follow-up (median: 39.8 vs. 14.4 ml)." (PMID 33123072, 2020). "Thus, we conclude that hs-CRP is a good indicator for hematoma volume." (PMID 33123072, 2020).
hematoma (continued). "The early presence of CRP—which could reflect either the local synthesis triggered by the hematoma or the conversion of the circulating soluble pentameric form to its insoluble and monomeric form—further supports the active role of CRP in defining the extent of damage." (PMID 30254628, 2018). "C-reactive protein (CRP) is acute-phase proteins induced by inflammatory factors, plasma CRP have been proven to be an independent predictor of ICH outcome, early hematoma growth and early neurological worsening." (PMID 40703780, 2025). "In the present study, elevated admission serum IL-12 levels are closely related to the inflammation (CRP and TNF-α), hematoma volume, and prognosis in ICH patients, substantializing serum IL-12 levels is an inflammation and prognostic biomarker for ICH." (PMID 36303589, 2022). "NIHSS score, hematoma volume, brain edema, NLR, and CRP on days 1, 7, and 14 after intracerebral hemorrhage of patients." (PMID 33392188, 2020). "Admission and 72-h CRP levels were found to be the main determinants of 6-months functional outcome and overall survival, alongside baseline GCS, hematoma volume, and total leukocytes." (PMID 30254628, 2018). "(2023) revealed that the blood inflammatory parameters including C-reactive protein (CRP) and neutrophil-to-lymphocyte ratio (NLR) could be employed as predictors for hematoma expansion and ICH prognosis." (PMID 39963412, 2025). "The studies also suggest that the later values of CRP and not the admission ones, better correlate with the hematoma volume, with the functional outcome." (PMID 35762501, 2023). "We also did not consider other factors such as blood gas, hematoma volume, C-reactive protein levels, D-dimer and thyroid-stimulating hormone in the study." (PMID 32776246, 2021). "Next, all variables, including gender, sex, baseline hematoma volume, hematoma location, time from onset to initial NCCT, GCS scores, NIHSS scores at baseline, spot signs, HE, SBP, and hs-CRP levels, were applied into a stepwise-forward logistic regression for the clinical outcome 1 year after ICH." (PMID 33123072, 2020). "However, the progression of IMHB is unpredictable, ranging from complete resolution to abrupt rupture, although numerous predictors of IMHB evolution, such as maximum aortic diameter (≥4.0 cm), hematoma thickness (≥10 mm), ULP development and an elevated CRP level (7.2 mg/dl), have been summarized." (PMID 36330007, 2022).